RUFY3 (RUN and FYVE domain containing 3)
Diseases named in the same sentence as RUFY3 in open-access papers (continued):
Sharing a sentence is not in itself a finding about the gene and the disease.
cancer (11 papers, 2015 to 2023). A tumor composed of atypical neoplastic, often pleomorphic cells that invade other tissues. "RUFY3 variant 2 (NM_014961.5, NP_055776.1; 469 amino acids in length) is the only functionally characterized RUFY3 isoform and regulates polarity and axon growth in neurons, as well as cancer cell migration and invasion." (PMID 35314681, 2022). "After establishing the cellular localization of HPIP, Rab5, and RUFY3, we next focused on the functional significance of their interaction in cancer cells." (PMID 37797694, 2023). "In CRC, RUFY3 is significantly up-regulated in cancer tissues compared with adjacent non cancer tissues, and plays a key role in cell invasion and metastasis." (PMID 34510031, 2021). "It is worth noting that recent studies have shown that RUFY3 plays an important role in gene transcription regulation and promotes malignant biological behaviors of various cancers, such as cell growth and invasion." (PMID 34510031, 2021). "Transgenic integration of TK5-F1-28 was in E region of chromosome 5, located in the intron of Rufy3 which is known to suppress formation of surplus axons for neuronal polarity, and is indicated in relating to carcinoma." (PMID 30060537, 2018). "HOXD9 has been shown to promote cancer development via transcriptional activation of oncogenes, such as RUN and FYVE domain containing 3 (RUFY3), Snail family transcriptional repressor 1 (SNAI1), Sodium channel epithelial 1α subunit (SCNN1A) and Hemicentin 1 (HMCN1)." (PMID 36907878, 2023). "Our findings suggest that the functions of RUFY3 in neurons and cancer cells, and RUFY4 in phagocytic cells, might be related to the ability of these proteins to couple endolysosomes to dynein-dynactin." (PMID 35314674, 2022). "The shorter RUFY3.2 is the only RUFY3 spliceform characterized to date, with previous studies showing that it plays roles in neuronal polarity and axon formation/degeneration, and in cancer cell migration, invasion, and metastasis." (PMID 35314674, 2022). "Recently, RUFY3 also seems to play a crucial role in promoting cancer development." (PMID 34510031, 2021). "Some other studies have also shown that RUFY3 plays various roles in different malignant tumors." (PMID 31772661, 2019). "We found that RUFY3-positive signals were present of cancer cells." (PMID 28623323, 2017). "Up to date, the function of RUFY3 has been rarely reported, especially in cancer cells." (PMID 25766321, 2015). "Among the six transcript variants of RUFY3 annotated on NCBI, only variant 2 (469 amino acids long) is functionally characterized and shown to regulate axon guidance in neurons and migration of cancer cells, processes that depend on actin cytoskeletal dynamics." (PMID 35314681, 2022). "Indeed, processes such as the regulation of axonal functions, cancer cell migration, invasion and metastasis, and autophagy have all been shown to be influenced by endolysosome positioning and motility, consistent with a role for RUFY3 and RUFY4 in the regulation of endolysosomal functions." (PMID 35314674, 2022). "RUFY3 and FOXK1 were expressed at high and intermediate levels, respectively, in the cytoplasm and nucleus of cancer cells." (PMID 28623323, 2017). "To validate our findings in vivo, we investigated the correlation between RUFY3 and FOXK1 expression in 91 pairs of adjacent normal colon mucosal tissues and cancer tissues." (PMID 28623323, 2017). "We first showed that RUFY3 protein expression was significantly increased in the SW1116, LoVo, SW480, CoCo2, DLD1 and SW620 cancer cell lines compared with the expression in a normal human colon cell line (FHC)." (PMID 28623323, 2017). "In 35 pairs of cases, the RUFY3 mRNA and protein levels in cancer tissues were significantly higher than those in adjacent normal tissues." (PMID 34510031, 2021). "Moreover, both HOXD9 and RUFY3 were highly expressed in cancer cells but not in normal gastric tissues, with their expressions being positively correlated." (PMID 31547840, 2019).
cancer (continued). "In previous study, the relationship between RUFY3 and PAK1 pathways in cancer has not been described." (PMID 25766321, 2015).
tumor (7 papers, 2015 to 2024). "Clinical analysis indicated that RUFY3 expression was positively associated with tumor size, microvascular invasion, TNM stage and Edmonson stage." (PMID 34510031, 2021). "A review of the related literature and KEGG pathway analysis revealed that RUFY3 is closely related to tumorigenesis and tumour development; therefore, we selected RUFY3 for subsequent experimental investigation." (PMID 38915053, 2024). "First, after prediction via the online PrePPI database, we found that RUFY3 can bind to key proteins in multiple tumour-related pathways." (PMID 38915053, 2024). "Western blot analysis revealed that the expression level of RUFY3 in the nude mouse tumours was consistent with that in the cells." (PMID 38915053, 2024). "Herein, we found that the expression of RUFY3 in HCC was higher than that in adjacent non tumor tissues." (PMID 34510031, 2021). "Our results indicated that high levels of RUFY3 significantly correlated with tumor size, microvascular invasion, clinical stage, and poor prognosis for HCC patients." (PMID 34510031, 2021). "LV-HOXD9 cell groups was increased compared to that in LV-vector cells, whereas RUFY3 knockdown decreased the proliferation rate and tumor vessel density in the HOXD9-overexpressing group." (PMID 31547840, 2019). "We showed that RUFY3 expression was higher in tumor tissues and that high expression level was bad for the patient prognosis." (PMID 31772661, 2019). "We identified that HOXD9 directly regulates RUFY3 expression in GC and sequentially promotes tumor proliferation, metastasis and invasion." (PMID 31547840, 2019). "The HOXD9 protein may enhance the malignant properties of tumor cells via its transactivation of the RUFY3 proto-oncogene." (PMID 31547840, 2019). "RUFY3 appears to play an important role in multiple Ras-like GTPase tumor pathways." (PMID 31547840, 2019). "We knew that RUFY3 or FOXK1 has been correlated with the malignant of tumor cells." (PMID 28623323, 2017). "Therefore, HOXD9 may play a critical role in RUFY3-mediated tumor growth and metastasis in vitro and in vivo." (PMID 31547840, 2019). "In this study, we found that circSORBS1 regulates RUFY3 mRNA expression and that the RUFY3 protein targets the YWHAE protein, which in turn affects the level of apoptosis in tumour cells." (PMID 38915053, 2024). "We observed that RUFY3 knockdown in HCCLM3 cell markedly decreased while RUFY3 overexpression in SMMC7721 cell significantly increased tumor mass and tumor volume." (PMID 34510031, 2021). "RUFY3 expression is up-regulated in the vast majority of detected tumor samples compared with the para-carcinoma non-cancerous tissues from the same patient." (PMID 31772661, 2019). "But there was no statistical difference about the tumor size (P=0.962), However, there was statistical difference in the expression of RUFY3 in different TNM staging tissues (P<0.01)." (PMID 31772661, 2019). "From this we can conclude that RUFY3 mainly play roles in the lymph node metastasis rather than promoting tumor growth." (PMID 31772661, 2019). "Furthermore, RUFY3 and FOXK1 expression were correlated with tumor progression and represented significant predictors of overall survival in CRC patients." (PMID 28623323, 2017). "However, the effects of the interaction between RUFY3 and FOXK1 on EMT and tumor invasion/metastasis for CRC remain unknown." (PMID 28623323, 2017).
bacterial infection (1 paper, 2023). "RUFY3 deficiency in lung phagocytes impacts therefore only transiently the response to bacterial infection." (PMID 37463962, 2023).
gastrointestinal tumors (1 paper, 2022). "Previous research on Rufy3 in tumors mainly focused on gastrointestinal tumors." (PMID 35461284, 2022).
RUFY3 also shares sentences with these, for which no sentence is quoted: bacterial pneumonia (1 paper); Cognitive impairment (1); infection (1); invasive carcinoma (1); osteosarcoma (1); Stroke (1).